GRIN3B (glutamate ionotropic receptor NMDA type subunit 3B)
Description:
Component of a non-conventional N-methyl-D-aspartate (NMDA) receptors (NMDARs) that function as heterotetrameric, ligand-gated cation channels with low calcium permeability and low voltage-dependent block by Mg(2+) (By similarity). Forms glutamatergic receptor complexes with GluN1 and GluN2 subunits which are activated by glycine binding to the GluN1 and GluN3 subunits and L-glutamate binding to GluN2 subunits (By similarity). Forms excitatory glycinergic receptor complexes with GluN1 alone which are activated by glycine binding to the GluN1 and GluN3 subunits. GluN3B subunit also binds D-serine and, in the absence of glycine, activates glycinergic receptor complexes, but with lower efficacy than glycine (By similarity). Each GluN3 subunit confers differential attributes to channel properties, including activation, deactivation and desensitization kinetics, pH sensitivity, Ca2(+) permeability, and binding to allosteric modulators (By similarity).
Synonyms: GluN3B; NR3B
Tractability: Small molecule: an approved drug acts on it; a high-quality ligand is known; it belongs to a druggable protein family. Antibody: UniProt places it where antibodies can reach, with medium confidence; UniProt predicts a signal peptide or a membrane-spanning region; its Gene Ontology location is reachable by antibodies, with medium confidence. PROTAC: its protein half-life has been measured; a small molecule that binds it is known. Other modalities: a drug acting on it is in phase 2 or 3 trials.
Safety:
Unwanted effects reported when the protein is acted on. In parentheses: how it was acted on, where the effect was seen, and who reports it.
ataxia (inhibition, acute dosing; central nervous system, cardiovascular; source: Lynch et al. (2017))
convulsions (activation, acute dosing; central nervous system, cardiovascular; source: Lynch et al. (2017))
decreased convulsions (inhibition, acute dosing; central nervous system, cardiovascular; source: Lynch et al. (2017))
decreased memory (inhibition, acute dosing; central nervous system, cardiovascular; source: Lynch et al. (2017))
decreased pain (inhibition, acute dosing; central nervous system, cardiovascular; source: Lynch et al. (2017))
dizziness (inhibition, acute dosing; central nervous system, cardiovascular; source: Lynch et al. (2017))
drug abuse/dependence (inhibition, acute dosing; central nervous system, cardiovascular; source: Lynch et al. (2017))
impaired social interactions (inhibition, chronic dosing; central nervous system, cardiovascular; source: Lynch et al. (2017))
increased blood pressure (inhibition, acute dosing and activation, acute dosing; central nervous system, cardiovascular; source: Lynch et al. (2017))
increased heart rate (inhibition, acute dosing; central nervous system, cardiovascular; source: Lynch et al. (2017))
increased locomotor activity (inhibition, acute dosing; central nervous system, cardiovascular; source: Lynch et al. (2017))
increased then decreased heart rate (activation, acute dosing; central nervous system, cardiovascular; source: Lynch et al. (2017))
neurodegeneration (inhibition, chronic dosing; central nervous system, cardiovascular; source: Lynch et al. (2017))
neurotoxicity (inhibition, acute dosing; central nervous system, cardiovascular; source: Lynch et al. (2017))
pain (activation, acute dosing; central nervous system, cardiovascular; source: Lynch et al. (2017))
psychosis (inhibition, chronic or acute dosing; central nervous system, cardiovascular; source: Lynch et al. (2017))
stereotypy (inhibition, chronic dosing; central nervous system, cardiovascular; source: Lynch et al. (2017))
Gene: Protein-coding gene on chromosome 19 (1,000,419 to 1,009,732, forward strand). Ensembl gene ENSG00000116032.
Subcellular location: Cell membrane; Postsynaptic cell membrane
Pathways (Reactome):
Neuronal System: Assembly and cell surface presentation of NMDA receptors
Gene Ontology:
Molecular function: ligand-gated monoatomic ion channel activity involved in regulation of presynaptic membrane potential; calcium channel activity; glutamate receptor activity; glycine binding; glycine-gated cation channel activity; monoatomic cation channel activity; neurotransmitter receptor activity; NMDA glutamate receptor activity; transmitter-gated monoatomic ion channel activity; transmitter-gated monoatomic ion channel activity involved in regulation of postsynaptic membrane potential; ligand-gated monoatomic ion channel activity; monoatomic ion channel activity; signaling receptor activity
Biological process: ionotropic glutamate receptor signaling pathway; modulation of chemical synaptic transmission; monoatomic cation transmembrane transport; protein insertion into membrane; regulation of calcium ion transport; regulation of synaptic plasticity; synaptic transmission, glutamatergic; calcium ion transmembrane transport; monoatomic ion transport; regulation of postsynaptic membrane potential; regulation of presynaptic membrane potential
Cellular component: neuronal cell body; neurotransmitter receptor complex; NMDA selective glutamate receptor complex; plasma membrane; postsynaptic density membrane; postsynaptic membrane; presynaptic membrane; membrane
Genetic constraint (gnomAD): Loss-of-function variants: 78 observed, 53.59 expected, observed/expected ratio (o/e) 1.46, 90% interval 1.21 to 1.75. The synonymous counts are far from expectation, so gnomAD's model fits this gene poorly and the ratio says little. Missense variants: 1,770 observed, 1,275.1 expected, observed/expected ratio (o/e) 1.39, 90% interval 1.33 to 1.44. Synonymous variants: 813 observed, 597.92 expected, observed/expected ratio (o/e) 1.36, 90% interval 1.28 to 1.44.
Homologues: Orthologues: chimpanzee GRIN3B (97% identical), macaque GRIN3B (94% identical), pig GRIN3B (83% identical), dog GRIN3B (80% identical), rat Grin3b (76% identical), mouse Grin3b (76% identical), guinea pig GRIN3B (68% identical), tropical clawed frog grin3b (55% identical), zebrafish grin3ba (54% identical), zebrafish grin3bb (48% identical), Caenorhabditis elegans nmr-2 (23% identical), Drosophila melanogaster Nmdar2 (22% identical), and 37 more. Paralogues in human: GRIN3A (49% identical), GRIN2C (24% identical), GRIN2B (24% identical), GRIN2D (24% identical), GRIN2A (24% identical), GRIN1 (18% identical), GRIK5 (17% identical), GRIA4 (17% identical), GRIK1 (17% identical), GRIK3 (17% identical), GRIA1 (16% identical), GRIK2 (16% identical), and 5 more.
Diseases named in the same sentence as GRIN3B in open-access papers:
GRIN3B is named in the same sentence as 26 diseases in open-access papers, as found by Europe PMC text mining. Sharing a sentence is not in itself a finding about the gene and the disease. The quoted sentences say what the papers report.
schizophrenia (12 papers, 2012 to 2025). A major psychotic disorder characterized by abnormalities in the perception or expression of reality. "Comparably, the GRIN3B gene, has been implicated in schizophrenia, general developmental disorders, and, notably, ASD." (PMID 39519104, 2024). "In this work, the authors found a SNP RS2240158 of GRIN3B was significantly associated with mismatch negativity, a proposed endophenotype of schizophrenia, in healthy subjects." (PMID 25768306, 2015). "From these observations, we conclude that the insCGTT variation of GRIN3B results in a functionally null NR3B protein, which constitutes a risk factor for schizophrenia." (PMID 25768306, 2015).
Anxiety (4 papers, 2009 to 2021). Intense feelings of nervousness, tension, or panic often arise in response to interpersonal stresses. "We previously found that the Grin3b knockout mouse have a phenotype suggestive of increased anxiety, such as decreased entry and time spent in the open arm of the elevated plus maze task." (PMID 25768306, 2015).
psychotic disorder (3 papers, 2017 to 2021). An abnormal condition of the mind that involves a loss of contact with reality. "More recently, a whole genome sequencing study in subjects with a high familial loading for psychotic disorders over three generations found a frameshift mutation (rs10666583) in the GRIN3B gene, which codes for the GluN3B subunit of the NMDAR." (PMID 32477178, 2020). "We found that 14 out of 22 patients affected by psychotic disorder had this GRIN3B variant (GF = 0·63)." (PMID 28132660, 2017). "In this highly affected family, we found a frameshift mutation (rs10666583) in the GRIN3B gene, which codes for the GluN3B subunit of the NMDA receptor in all family members with a psychotic disorder, but not in the healthy relatives." (PMID 28132660, 2017).
breast invasive carcinomas (1 paper, 2022). "Moreover, in breast invasive carcinomas, GRIN2B and GRIN3B are two GRIN genes mostly expressed." (PMID 36139568, 2022).
COVID-19 (1 paper, 2023). A disease caused by infection with severe acute respiratory syndrome coronavirus 2. "Autoantibodies are more common in COVID-19 than controls and some (including against MYL7, UCH-L1, and GRIN3B) are more frequent with altered consciousness." (PMID 38135686, 2023).
heroin addiction (1 paper, 2021). "Our study identified variations in five candidate genes, including GRIN3A, GRIN3B, CYP2C19, TPH2, and COMT, contributing to susceptibility to heroin addiction." (PMID 33915886, 2021). "GRIN3A and GRIN3B may play roles in heroin addiction, acting as dominant-negative modulators of NMDA receptors." (PMID 33915886, 2021).
prostate carcinoma (1 paper, 2017). A carcinoma that arises from epithelial cells of the prostate gland. "Other genes found to be H3K27me3-enriched in prostate cancer tissues compared to normal tissues include MYO1D, TENM4, GRIN3B, all of which are involved in cell communication and cell adhesion." (PMID 28403887, 2017).
psychiatric disorder (3 papers, 2013 to 2025). A disorder characterized by behavioral and/or psychological abnormalities, often accompanied by physical symptoms. "This hypothesis can be further supported by the whole genome sequencing of familial psychiatric disorders, which found the frameshift mutation of GRIN3B-rs10666583 was significantly higher than that of the healthy controls." (PMID 40235311, 2025).
GRIN3B also shares sentences with these, for which no sentence is quoted: brain ischemia (2 papers); amyotrophic lateral sclerosis (1); autism (1); Autoimmunity (1); breast carcinoma (1); cancer (1); Cerebral ischemia (1); cognitive deficits (1); depression (1); epilepsy (1); Intellectual disability (1); melanoma (1); memory impairment (1); mental disorder (1); motor neuron disease (1); neurodegenerative disease (1); neurodevelopmental disorder (1); Obesity (1).